ATG5 (autophagy related 5)
Diseases named in the same sentence as ATG5 in open-access papers (continued):
Sharing a sentence is not in itself a finding about the gene and the disease.
asthma (continued). "This study aimed to evaluate ATG5 levels and its clinical roles in adult asthma patients." (PMID 37644509, 2023). "Autophagy-related 5 (ATG5) gene transcript variants are associated with the development of childhood asthma, and the polymorphisms of ATG5 and ATG7 are associated with neutrophilic airway inflammation in asthma." (PMID 35903102, 2022). "Still, subsequent studies did not detect an association of ATG5 gene polymorphisms with asthma severity but only with higher sputum neutrophil numbers." (PMID 34204710, 2021). "Therefore, we suggest that ATG5 plays an important role in the ability of respiratory epithelium to increase autophagy and protect against asthma." (PMID 30154478, 2018). "We hypothesized that ATG5 and ATG7 polymorphisms and/or dysregulated expression of these genes are associated with childhood asthma." (PMID 22536318, 2012). "Collectively, our results suggest a novel function for ATG5 in asthma." (PMID 22536318, 2012). "Taken together, these studies provide a potential mechanism for a role of ATG5 in asthma." (PMID 22536318, 2012). "Based on our results thus far, we hypothesized that ATG5 expression would be increased in patients with asthma." (PMID 22536318, 2012). "However, further studies reported higher levels of Atg5, Beclin-1, and p-62 in the epithelial cells from lung sections of the large airways of asthma patients than in large airway smooth muscles (ASMs) when compared with healthy controls without the activation of autophagy." (PMID 37627282, 2023). "Notably, ATG5 participates in the pathogenesis of asthma by mediating the differentiation of CD4+ T cells, which suggests that it may have a potential relationship with Th1 and Th2 cells in asthma patients." (PMID 37644509, 2023). "However, the previous studies have only shown an abnormal expression of ATG5 in asthma children." (PMID 37644509, 2023). "The possible explanation was as follows: ATG5 could upregulate Th2 cell differentiation and inhibit Th1 cell differentiation by regulating cytokine secretion and antigen presentation, thus destroying Th2/Th1 balance in adult asthma patients." (PMID 37644509, 2023). "Human polymorphisms in Atg5 and Atg7 are not linked to susceptibility to or severity of asthma, but they are linked with neutrophilic inflammation in the sputum of asthmatic patients, suggesting a link to non-Th2 asthma." (PMID 37627282, 2023). "In addition, asthma patients with a genetic variant in Atg5 (SNP rs12212740 G > A of Atg5) from peripheral blood samples showed aggravated lung function compared with other asthma patients without this genetic variant." (PMID 35392563, 2022). "Thus, miR-30a expression inversely correlates with autophagy in asthma, supporting the hypothesis that lower miR-30a levels lead to the overexpression of ATG5, which promotes asthma progression." (PMID 35455659, 2022). "Polymorphisms of Atg5 and Atg7 are not linked to asthma susceptibility or severity, but are associated with neutrophilic inflammation in sputum, suggesting a link to non-T2 asthma." (PMID 35608088, 2022). "Autophagy‐related genes, such as ATG5, Beclin‐1 (BECN1), and LC3, are involved in and regulate the pathogenesis of asthma." (PMID 39949885, 2025). "In the current study, ATG5 was positively correlated with TNF-α, IL-1β, IL-6, and IL-17 in adult asthma patients." (PMID 37644509, 2023). "Another study indicates that ATG5 promotes airway smooth muscle cell (ASMC) inflammation, fibrosis, and autophagy, leading to asthma." (PMID 37644509, 2023). "Autophagy protein 5 (ATG5) regulates airway epithelial cell autophagy, immune response, and inflammation, which is involved in asthma progression." (PMID 37644509, 2023). "Inhibition of autophagy in rats treated with 3-methyladenine or knockdown of ATG5 inhibited the expression of eosinophils and interleukin (IL)-5 in the bronchoalveolar lavage fluid (BALF), thereby alleviating asthma symptoms." (PMID 36330226, 2022).
asthma (continued). "ATG5, Beclin1, and LC3BII/I were significantly upregulated in asthma mice, which were greatly suppressed by the introduction of YFP, indicating that YFP ameliorated the autophagy in the lung of the mouse asthma model." (PMID 33542675, 2021). "Previous studies have shown that ATG5 is involved in the autophagosome formation, which would form complex with ATG12 and ATG16L1, in patients with refractory asthma." (PMID 33643037, 2020). "In fact, there is a strong correlation between autophagy activation and airway remodeling in asthma, with a higher expression of Beclin 1 and Atg5 along with reduced p62 in asthmatics compared with non-asthmatics." (PMID 37627282, 2023). "Inhibiting ATG5-mediated autophagy can reduce airway inflammation and AHR in asthma." (PMID 37919667, 2023). "Autophagy protein 5 (ATG5), one of the key proteins regulating autophagy activity, is considered to play an important role in the pathogenesis of asthma by regulating Th cell differentiation, inflammation, airway epithelial cell autophagy, and airway remodeling." (PMID 37644509, 2023). "Furthermore, the expression of ferritinophagy-related proteins (NCOA4, ATG-5, and ATG-7) in the lung tissues was elevated upon the occurrence of asthma but was then repressed after the treatment of Ferr-1 and 3-MA." (PMID 35154576, 2022). "Also, the levels of beclin-1 and ATG5 were increased and the level of P62 was decreased in the OVA group, indicating that autophagy was activated in asthma." (PMID 33413331, 2021). "Challenge with HDM also demonstrated the same neutrophilic asthma phenotype as the WT suggesting that the initiation of asthma in Atg5−/− mice does not need to be provoked with allergen." (PMID 32733448, 2020). "Furthermore, two candidate gene association studies detected associations between variations in the gene encoding ATG5 and asthma, and elevated ATG5 gene expression was found in the nasal epithelium of children with acute asthma as compared to those with no asthma or stable asthma." (PMID 28424691, 2017). "Using genetic and experimental approaches, we examined the association of 13 HapMap-derived tagging SNPs in ATG5 and ATG7 with childhood asthma in 312 asthmatic and 246 non-allergic control children." (PMID 22536318, 2012). "However, no study has explored ATG5 level and its relationship with clinical features in adult asthma patients." (PMID 37644509, 2023). "Therefore, we compared Atg5 gene expression in nasal mucosal cells (>92% airway epithelial cells) isolated from children with acute or stable asthma, as well as from non-asthmatic control children." (PMID 22536318, 2012). "Moreover, the clinical roles of ATG5 in adult asthma patients have not been explored." (PMID 37644509, 2023). "In sharp contrast, recent studies showed that ATG5 expression in airway epithelium, ASM, and inflammatory cells was not increased in asthmatics and did not correlate with asthma severity or lung function." (PMID 34204710, 2021). "Our data support a role for the autophagy pathway, and specifically ATG5 but not ATG7, in childhood asthma." (PMID 22536318, 2012). "Interestingly, expression of BECN1 and ATG5 has been found to be increased, together with reduced expression of SQSTM1, in the large airway smooth muscle of patients with asthma compared with healthy individuals without asthma." (PMID 34572117, 2021). "In terms of lung function in asthmatic subjects, ATG5 protein expression did not correlate with FEV1% predicted in asthmatic subjects [Spearman’s rank correlation coefficient (ρ) = 0.04, p = 0.83] or when stratified by asthma severity (0.3 < Spearman’s ρ < 0.8, 0.26 < p < 0.83) (data not shown)." (PMID 28424691, 2017).
glioma (37 papers, 2015 to 2024). A benign or malignant brain and spinal cord tumor that arises from glial cells (astrocytes, oligodendrocytes, ependymal cells). "Similar to glioma, AEG-1-induced autophagy, AMPK/ATG5 signaling and an increase in MDR1 have been implicated to confer 5-FU resistance in gastric cancer." (PMID 33918653, 2021). "The deletion or lower expression of important genes (Beclin-1, FIP200, blood-inducing factor 1 (Bif1), UVRAG, Atg4c and Atg5) is reported in gliomas for autophagosome initiation and elongation." (PMID 33525678, 2021). "In this study, we found that blocking autophagy with 3MA, bafilomycin A1 or by knocking down ATG5 with SiRNA not only inhibited silibinin-induced glioma cell death, but also prevented mitochondrial accumulation of superoxide and nuclear translocation of AIF." (PMID 32801360, 2020). "To further verify the role of autophagy in silibinin-induced glioma cell death, we knocked down ATG5 with SiRNA and examined its effect on glioma cell death." (PMID 32801360, 2020). "The results showed that mRNA expression of ATG3 (HR = 0.63, 95% CI: 0.40–0.99, p = 0.05), ATG4C (HR = 1.54, 95% CI: 1.16–2.01, p = 3 × 10− 3) and ATG5 (HR = 0.61, 95% CI: 0.43–0.86, p = 5 × 10− 3) were independent OS prognostic factors in gliomas patients." (PMID 31291988, 2019). "Rapamycin, an inhibitor of the mTOR signaling pathway, promoted malignant glioma cell death and sensitized glioma to combined radiotherapy or temozolomide treatment by autophagic activation along with increased expression of Beclin-1, Atg5 and LC3-II45." (PMID 30302016, 2018). "EMAP-II upregulated ATG7 and ATG5 to enhance U87 and U251 glioma cell autophagy via miR20a down-regulation." (PMID 29632473, 2018). "On the other hand, autophagy inhibition via adding pharmacological inhibitors or silencing Beclin-1/ATG-5 significantly potentiated LY3023414-induced glioma cell apoptosis." (PMID 29228741, 2017). "The formation of GFP-LC3 puncta was observed in wild-type U2OS and human glioma H4 cells but not in cells that are deficient for the essential autophagy protein ATG5 and which acts upstream of LC3 to facilitate lipidation and membrane association." (PMID 33414432, 2021). "Furthermore, autophagy inhibition has been observed in 3-MA or ATG5 siRNA-treated U251 glioma cells." (PMID 34204169, 2021). "Moreover, inhibition of ATG5 expression in glioma cell models strongly reduced cell mobility with increased chemosensitivity under hypoxia suggesting that this gene was also associated with aggressiveness in different cancer models." (PMID 33488952, 2020). "Besides these pharmacological evidences, our results further showed that silencing Beclin-1/ATG-5 also significantly potentiated LY3023414-induced glioma cell death and apoptosis." (PMID 29228741, 2017). "Immuno-fluorescence analysis showed high levels of Atg5 expression which indicated that Atg5 might be useful a surrogate marker of the anti-glioma effect." (PMID 26309786, 2015). "Therefore, in the current work, by manipulating autophagy in glioma using 3-MA inhibiting autophagosome formation or transfecting ATG5 siRNA, we discovered that the inhibition of autophagy attenuated the radiation sensitization effects mediated by the silencing of IRAK1-PRDX1 axis." (PMID 37031183, 2023). "Thus, silencing Beclin-1 or ATG-5 could also efficiently sensitize LY3023414's activity in glioma cells." (PMID 29228741, 2017). "In addition, we also showed that glioma tissues expressed higher levels of ATG5 and FIP200." (PMID 26536662, 2015). "The reduced phosphorylation levels of Akt and mTOR in IRAK1 depletion glioma cells were restored by PRDX1 overexpression, ATG5 knockdown or 3-MA treatment." (PMID 37031183, 2023). "We also further evaluated a range of autophagy-related proteins, including mTOR, p-mTOR, ATG5, ATG12 and Beclin-1 in glioma cells." (PMID 34683892, 2021).
glioma (continued). "In that study, the isolated glioma cells expressed high viability, which correlated with the expression of isoform II of LC3, ATG5 and ATG12, known for their contribution to pro-survival autophagy." (PMID 33525678, 2021). "It was found that knockdown of ATG5 not only prevented silibinin-induced upregulation of LC3-II and downregulation of p62 (SQSTM1), but also inhibited glioma cell death." (PMID 32801360, 2020). "In vitro studies reveal that blocking autophagy with 3MA, bafilomycin A1 or by knocking down ATG5 with SiRNA inhibits silibinin-induced mitochondrial accumulation of superoxide, AIF translocation from mitochondria to nuclei and glioma cell death." (PMID 32801360, 2020). "In vitro studies revealed that blocking autophagy with 3MA1, bafilomycin A1 or by knocking down ATG5 with SiRNA inhibited silibinin-induced mitochondrial accumulation of superoxide, AIF translocation from mitochondria to nuclei and glioma cell death." (PMID 32801360, 2020). "We have investigated different autophagy markers, such as Atg5, Atg7, Beclin-1, LC3A/B, and p62, from all three GBM cell lines (U-87MG, GL261, and F98), and from C6-glioma and N2a cells." (PMID 30669284, 2019). "To study the role of miR-129- and E2F7-induced autophagy on viability of glioma cells, we performed MTT assay by using 3-MA, Beclin-1 siRNA (sibeclin-1) or Atg5 siRNA (siAtg5) to block autophagic flux, respectively." (PMID 26824182, 2016). "EMAP-II up-regulated the expression of the proteins LC3-II/I, ATG7 and ATG5, but down-regulated P62/SQSTM1 expression in the U-87 and U-251 glioma cells, demonstrating that the antitumor activity results from the induction of autophagy, not apoptosis." (PMID 27242439, 2016). "In this paper, we also found that ATG5 and FIP200 were more highly expressed in clinical glioma tissues compared with normal brain tissue." (PMID 26536662, 2015). "The overexpression of AEG-1-induced protective autophagy in multiple cell types by activating the AMPK/mTOR pathway led to increased expression of the autophagy regulator ATG5, and knocking down AEG-1 in glioma cells significantly increased their sensitivity to doxorubicin." (PMID 33918653, 2021). "Moreover, knockdown of Beclin-1, VPS34, and ATG5 can inhibit autophagy in IR-induced cell death in U87MG, U373MG, and LN229 glioma cells." (PMID 34204169, 2021). "We observed that the selective knockdown of ULK1, Atg5, or Atg7 or pharmacological inhibition of autophagy with 3MA increased the levels of active caspase 3, 7 and PARP degradation in WIN55,212-2-treated LN18 glioma cells." (PMID 33499365, 2021). "EMAP-II induced the autophagy of human U-87 and U-251 glioma cells, which might be correlated with the up-regulation of ATG7 and ATG5." (PMID 27242439, 2016). "Furthermore, we observed that miR224-3p levels inversely correlated with the protein levels of ATG5 and FIP200 (P < 0.01), which definitely indicated that miR224-3p regulates ATG5 and FIP200 in glioma tissues." (PMID 26536662, 2015). "Therefore, EMAP-II may up-regulate expression of ATG5 and ATG7 via down-regulation of miR-20a, inducing autophagy in glioma cells." (PMID 27242439, 2016). "Additionally, in U-251 glioma cells, EMAPII (low-dose endothelial-monocyte-activating polypeptide-II) also downregulates miR-20a and induces autophagy by subsequently increasing the expression of ATG5 (autophagy-related 5) and ATG7, both of which are miR-20a targets." (PMID 36230953, 2022). "However, the expression of mTOR, p-mTOR, ATG5, ATG12 and Beclin-1 in glioma cells was not increased after Co3O4 NPs treatment, which confirmed that Co3O4 NPs did not induce autophagy." (PMID 34683892, 2021).
pancreatic cancer (35 papers, 2014 to 2025). "A study in 2019 showed that pancreatic cancer cells deficient in the autophagy gene Atg5 produced higher levels of chemokines and attracted more immune cells to pancreatic tumor tissue in mice than did pancreatic cancer cells with intact autophagy." (PMID 40231206, 2025). "In pancreatic cancer, Atg5 or Atg7 deficiency resulted in increased PanIN lesions, albeit lack of progression to malignant disease." (PMID 37735513, 2023). "Erastin-induced ferroptosis has been shown to be suppressed by Atg5 or Atg7 deficient mouse embryonic fibroblasts (MEFs), as well as in human pancreatic cancer and human fibrosarcoma cell lines with knockdown of Atg5 or Atg7 protein levels with shRNA." (PMID 31936109, 2020). "miR-137 promotes sensitivity of pancreatic cancer cells to ADR by inhibiting ATG5-mediated autophagy." (PMID 40781108, 2025). "The overexpression of miR-137 was reported to enhance doxorubicin’s effect on reducing pancreatic cancer cell survival by inhibiting autophagy mediated by ATG5." (PMID 38139352, 2023). "A recent study showed that miR-137 can increase chemotherapy sensitivity in pancreatic cancer cells by suppressing autophagy mediated by ATG5." (PMID 36552609, 2022). "Previously, it was reported that the protein level of Atg5 (autophagy-related 5) demonstrates positively correlated to the invasiveness of human pancreatic cancer." (PMID 35715752, 2022). "In keeping with this, in K‐rasG12D driven models of pancreatic cancer development, autophagy inhibition (via simultaneous deletion of Atg7 or Atg5) has shown to increase the incidence of early premalignant lesion development." (PMID 35689420, 2022). "The activation of the Atg5/Atg7-NCoA4 axis in pancreas cancer PANC-1 cells can degrade ferritin, inhibit the expression of the heavy chain of ferroprotein, and induce ferroptosis." (PMID 34413966, 2021). "To further explore the link between the inhibition of autophagy and cell viability by IMB-6G, we used siRNA against Atg5 to determine IMB-6G-induced apoptosis in pancreatic cancer cells." (PMID 28139733, 2017). "We confirmed that inhibition of autophagy using CQ, Atg5 siRNA, or deguelin induces increased cytotoxicity and apoptosis in pancreatic cancer cells." (PMID 28208617, 2017). "To determine the role of autophagy in pancreatic cancer stemness, we established lentivirus-mediated stable ATG5, ATG7, and BECN1 knockdown cell lines shATG5, shATG7, and shBECN1 derived from PANC-1 cells and analyzed their CSC activity." (PMID 26458814, 2015). "Although the proximity of Beclin1 to the BRCA1 tumor suppressor gene renders the interpretation difficult particularly in these tumor types, such a haplo‐insufficient tumor‐suppressive activity was also observed in the Atg5+/− mouse models for pancreatic cancer and AML." (PMID 35689420, 2022). "In line with our study, the ATG5 level is crucial for tumorigenesis of pancreatic cancer cells with oncogenic Kras, implying ATG5 may facilitate early tumor development in colorectal cancer." (PMID 33926066, 2021). "However, the protein level of ATG5 is positively related to the invasiveness of human pancreatic cancer, whereas the deletion of Atg5 inhibits tumor proliferation and metastasis in PDAC." (PMID 33937024, 2021). "The autophagy dependency of pancreatic cancer cells may lead to inhibition of cell proliferation after loss of autophagic components, such as EI24 and ATG5." (PMID 31396480, 2019). "Interestingly, another miRNA, miR-216a, that is also downstream of TGF-β signaling and miR-192, has been shown to target BECN1 and ATG5 expression in endothelial cells and Becn1 in pancreatic cancer cells." (PMID 29725042, 2018). "Additionally, to confirm whether THM induced autophagy in pancreatic cancer cells, we further assessed the expression levels of multiple autophagy-related proteins, including ATG5, ATG7, LAMP2, SQSTM1 and LC3B, in THM-treated cells." (PMID 40756353, 2025).